NOD2 (nucleotide binding oligomerization domain containing 2)
Diseases named in the same sentence as NOD2 in open-access papers (continued):
Sharing a sentence is not in itself a finding about the gene and the disease.
Crohn disease (continued). "The antimicrobial dysfunction (e.g. hBD-2) of intestinal epithelial cells to enteric bacteria (e.g. pathogenic adherent-invasive E. coli (AIEC)) in patients with NOD2 mutants predispose particularly to ileal involvement in Crohn’s Disease." (PMID 26893616, 2016). "Mutations of NOD2 have been associated with chronic inflammatory disorders such as Crohn's disease (CD), Blau syndrome (BS) and early-onset sarcoidosis (EOS), but little is known about its signalling mechanism and the role it plays in these diseases." (PMID 27283905, 2016). "Mutations in NOD2 have been associated with an increased risk of Crohn’s Disease (CD), a disabling inflammatory bowel disease (IBD)." (PMID 27812135, 2016). "This is a logical connection because defective NOD2 immunity has been associated with promoting other chronic pro-inflammatory pathologies, dysbiosis and human NOD2 variants have the highest risk association with Crohn's disease." (PMID 25666722, 2015). "Overall our data is consistent with the view that Crohn’s disease-associated NOD2 polymorphisms result in receptor dysfunction, but that the causes of this dysfunction are multi-factorial." (PMID 26500656, 2015). "In this work, we have analyzed 53 Crohn’s disease-associated SNPs for their effect on three key functional consequences of NOD2 stimulation, namely: basal and ligand-induced NFκB-driven signaling, interaction with RIPK2, and membrane localization." (PMID 26500656, 2015). "Of the more than 70 genes associated with Crohn’s disease, polymorphisms in NOD2 remain the single greatest genetic risk factor." (PMID 26500656, 2015). "NOD2 has been identified as a susceptibility gene for Crohn’s disease and different NOD2 polymorphisms have been associated with loss-of-function of the protein." (PMID 26287240, 2015). "Somewhat counter-intuitively all three of the major NOD2 polymorphisms associated with Crohn’s disease result in a loss of receptor function and reduced inflammatory signaling." (PMID 26500656, 2015). "Three non-synonomous polymorphisms – R702W, G908R, and L1007fsincC – account for around 80% of all NOD2-polymorphism associated cases of Crohn’s disease reported, with homozygotic mutation resulting in around a 10-fold greater risk than heterozygotic mutation." (PMID 26500656, 2015). "In total, 53 Crohn’s disease-associated polymorphisms were taken forward for functional characterization in conjunction with wild-type NOD2 and the inactive Walker-B mutant D379A as control constructs." (PMID 26500656, 2015). "Special emphasis has been given to the susceptibility to Crohn's disease, in association with abnormalities in the NOD2 and in the NLRP3/inflammasome." (PMID 25821356, 2015). "NOD2, which is an intracellular sensor of bacterial peptidoglycan, was identified as a susceptibility gene for Crohn's disease, and Crohn's disease-associated NOD2 mutations are associated with a loss of function of the protein." (PMID 26090491, 2015). "Our results are corroborated by the findings from one human study, which showed complete protection from severe aGVHD when the donor carried variants forms of NOD2 associated with Crohn’s disease." (PMID 25643148, 2015). "Insight into biological differences is supported by the observation that two risk loci for Crohn’s disease,NOD2 andPTPN22, are protective for ulcerative colitis." (PMID 27508055, 2015). "Polymorphisms in NOD2 represent the single greatest genetic risk factor for the development of Crohn’s disease." (PMID 26500656, 2015). "A previous study suggested an association of the single nucleotide polymorphism (SNP) rs72796353 (IVS4+10 A>C) in the NOD2 gene with susceptibility to Crohn’s disease (CD)." (PMID 26147989, 2015). "For example, variation at the NOD2 (caspase recruitment domain-containing protein 15) has been associated with susceptibility to Crohn’s disease." (PMID 25717144, 2015).
Crohn disease (continued). "For example, the Nod2 risk allele for Crohn's disease is associated with a decrease in α-defensin production by Paneth cells in humans, and NOD2-deficient mice also exhibit a decrease in α-defensin production." (PMID 26484345, 2015). "Genetic studies have reported numerous other polymorphisms in NOD2 that associate with Crohn’s disease." (PMID 26500656, 2015). "TLR9(T1237C) expression also has increased prevalence in Crohn’s disease, particularly among those with NOD2 mutations and IL23R variants." (PMID 26361369, 2015). "In inflammatory disease, increase of TLR2 expression induces NF-κB activation leading to exaggerated immune responses with production of inflammatory cytokines and such happens in Crohn's disease in which NOD2 is mutated." (PMID 26090491, 2015). "Our understanding of how NOD2 SNPs predispose to Crohn’s disease is improving and in general, they appear to result in defective NOD2 function." (PMID 26500656, 2015). "In 2001, variants of the NOD2 gene were associated with impaired mucosal barrier function in Crohn’s disease." (PMID 25887140, 2015). "We further demonstrate how eQTL in PADI4 and NOD2 delineate risk variant function in rheumatoid arthritis, leprosy and Crohn’s disease." (PMID 26151758, 2015). "To further investigate the importance of the NOD2 NACHT domain we tested the impact of a panel of Crohn’s Disease associated single nucleotide polymorphisms (SNP) spanning the NACHT on the interaction with CARD9." (PMID 24960071, 2014). "Disease associated polymorphisms in RIP2's upstream signaling partner, NOD2, have been described for early onset sarcoidosis and Crohn's disease." (PMID 24658576, 2014). "The fact that NOD2 is a susceptibility gene for Crohn's disease triggered our study for its potential role in HCMV recognition." (PMID 24671169, 2014). "Namely, Crohn's disease susceptibility gene NOD2 polymorphisms have been reported to be more prevalent in patients with graft failure following intestinal transplantation (IT)." (PMID 24465786, 2014). "In humans, mutations in Nod2 are associated with Crohn's disease, while mutations in the Rip2 locus are linked with systemic lupus erythematosus." (PMID 24733360, 2014). "Polymorphisms in ATG16L1 and NOD2 genes have been linked to Crohn's disease, an intestinal inflammatory disease." (PMID 24818040, 2014). "We have performed an in-depth morphological and immunohistochemical study on granuloma-containing biopsies from Blau patients as well as from patients with Crohn’s disease and NOD2 polymorphisms." (PMID 25136265, 2014). "Clinical relevance of mutations in the NOD2 gene arises from their association with Crohn’s disease." (PMID 24597572, 2014). "This phosphorylation event is necessary for effective NOD2 signaling and is blocked in the presence of the most common Crohn's disease-associated NOD2 allele." (PMID 24658576, 2014). "The role of NOD2 in these diseases has been illuminated by the identification of proteins, such as ATG16L1 and CARD9, which are both linked to Crohn's disease and interact with NOD2." (PMID 25520185, 2014). "NOD-like receptors have been associated to Crohn's disease, while other immune-related genes likely interacting with NOD2 have been associated to ulcerative colitis." (PMID 25211452, 2014). "Polymorphisms in NOD2 are the cause of the inflammatory disorder Blau syndrome and act as susceptibility factors for the inflammatory bowel condition Crohn's disease." (PMID 25520185, 2014). "Mutations in NOD2 are strongly associated with Crohn's disease, whereas mutations in NOD1 have been associated with asthma and atopic eczema." (PMID 24671169, 2014). "The first polymorphism associated with susceptibility to Crohn’s disease was identified in the innate immunity sensor gene NOD2 (nucleotide-binding oligomerization domain-containing protein 2) in 2001." (PMID 25256712, 2014).
Crohn disease (continued). "In 2001, a link between mutations in the NOD2 gene and Crohn’s disease was first established independently by two different groups." (PMID 24597572, 2014). "Despite these similarities, research on NOD2 has been more prominent, predominantly owing to the identification of numerous NOD2 single nucleotide polymorphisms (SNPs) which are associated with Crohn's disease or causal for Blau syndrome." (PMID 25520185, 2014). "Ever since the identification in 2001 of nucleolar oligomerization and binding domain 2 (NOD2) gene mutations in patients with Crohn's disease, it is considered that the genetic factor in IBD relates to defective innate immunity." (PMID 25191865, 2014). "Mutations of NOD2 gene have been linked to a number of chronic inflammatory diseases including Crohn’s disease, atopic dermatitis and so on." (PMID 24586700, 2014). "The IRGM polymorphisms were associated with Crohn's disease and the NOD2 polymorphisms were associated with ulcerative colitis." (PMID 25191865, 2014). "We observed the association between Crohn’s disease and NOD2 (rs17313265, 0.28 in CD, 0.19 in controls, OR 1.5, p = 9×10−6) and IL23R (rs11209026, 0.026 in CD, 0.0.071 in controls, OR 0.4, p = 3.8×10−4)." (PMID 25259511, 2014). "The relationship between CARD9 and NOD2 is particularly intriguing as the genes for both these proteins contain polymorphisms influencing susceptibility to Crohn’s Disease in humans." (PMID 24960071, 2014). "Accordingly, NOD2 was the first identified susceptibility gene for the inflammatory bowel disease termed Crohn's disease." (PMID 23818254, 2013). "NOD2 the most strongly associated gene with Crohn’s disease is responsible for pro-inflammatory cytokine release and autophagy induction." (PMID 23745122, 2013). "Several NOD2 loss-of-function mouse lines have been generated in an attempt to elucidate its role in Crohn’s disease." (PMID 24137163, 2013). "Mutations in the genes encoding NLRP3 or NLRP12 lead to hereditary periodic fever syndromes, while mutations in CARD15 that encodes NOD2 are linked to Crohn’s disease or Blau’s syndrome." (PMID 24137163, 2013). "NOD2 is of interest in human disease, as mutations in NOD2 are associated with Crohn's disease, Blau syndrome and early onset sarcoidosis." (PMID 23405246, 2013). "Mutations in the gene encoding NOD2 in humans have been associated with Crohn’s disease (CD), Blau syndrome (BS), and early onset sarcoidosis (EOS)." (PMID 24015287, 2013). "NOD2 genetic mutations in humans have been implicated in Crohn's disease, Blau syndrome, sarcoidosis, and graft-versus-host disease." (PMID 23675299, 2013). "Mutations in NOD2 are associated with Crohn's disease and one of its major risk alleles increases risk for CD in heterozygous individuals by 2.4 fold and in homozygous or compound heterozygous individuals by 17.1 fold." (PMID 23840689, 2013). "The NOD2 1007fsincC Crohn’s Disease susceptibility polymorphism lacks the last 33 amino acids and doesn’t membrane localize." (PMID 24109482, 2013). "This is a direct opposite of the loss of function seen in NOD2 associated with Crohn’s disease, although both conditions result in granuloma formation." (PMID 23745122, 2013). "In support of this possibility, the conserved glycine in NOD2 has been thoroughly investigated as a SNP (G908R) which predisposes to Crohn’s Disease and reduces the ability of NOD2 to respond to MDP." (PMID 24109482, 2013). "Other NOD2 mouse mutants were later generated to express common Crohn’s disease susceptibility mutations." (PMID 24137163, 2013). "Nod2 is mainly expressed in monocytes and macrophages, and mutations of NOD2 are associated with Crohn's disease, an inflammatory bowel disease mainly driven by T cells." (PMID 23382681, 2013). "Polymorphisms in NOD2 that predispose to Crohn's disease confer impaired NF-κB activation in response to NOD2 ligands, which results in chronic inflammation presumably because of an impaired clearance of invading bacteria." (PMID 23818254, 2013).
Crohn disease (continued). "Some current ideas about NOD2 polymorphisms in Crohn’s disease patients were previously reviewed and discussed elsewhere." (PMID 23162548, 2012). "The most common Card15 mutation associated with Crohn’s disease is an L100fs frameshift insertion at nucleotide 3020 (3020insC) in the LRR region of NOD2." (PMID 23162548, 2012). "These high coverage thresholds are backed by a simulation of the SNP detection performance at the NOD2 gene, which is associated with Crohn’s disease; it fell rapidly when the achieved coverage was below 40×." (PMID 22913592, 2012). "Following the early studies in Crohn's disease, polymorphisms throughout the NOD2 gene have been implicated in numerous diseases." (PMID 23119165, 2012). "In fact, it was recently demonstrated that the Crohn’s-disease-associated NOD2 mutation suppresses human IL-10 transcription by inhibiting the activity of the nuclear ribonucleoprotein hnRNP-A1." (PMID 23162548, 2012). "Studies have shown that NOD2 polymorphisms can affect the response to antibiotic treatment of perianal fistulas in Crohn's disease patients." (PMID 23119165, 2012). "Our finding of a significant negative statistical interaction between cigarette smoking and the 1007fs NOD2 polymorphism in patients with Crohn's disease is intriguing and warrants further investigation in epidemiological and functional studies." (PMID 22416979, 2012). "The most prevalent genetic defect associated with Crohn's disease is mutation in the intracellular pattern recognition receptor known as NOD2 (nucleotide binding oligomerization domain 2)." (PMID 24278738, 2012). "Nod2 is a cytoplasmic PRR that is genetically-associated with Crohn's disease and has been demonstrated to play an important role in pathogen defence in mouse models." (PMID 22272321, 2012). "Genetic variation in NOD2 and cigarette smoking are well-established risk factors for the development of Crohn's disease (CD)." (PMID 22416979, 2012). "Other mutations in NOD2, predominantly fs1007, are linked with the development of Crohn's disease (CD), a multifactorial inflammatory bowel disease." (PMID 22829933, 2012). "Nod2 was originally identified as a Crohn's disease susceptibility factor by linkage analysis that was subsequently confirmed in genome-wide association studies." (PMID 22272321, 2012). "Results of the parent-of-origin (POO) analysis for the NOD2 variants in Dutch Crohn’s disease trios (n = 111) and replication in German Crohn’s disease trios (n = 598)." (PMID 23028907, 2012). "Three NOD2 polymorphisms, identified as disease-associated variants in Crohn's disease, have recently been suggested as important candidate gene markers in the outcome of HSCT." (PMID 23119165, 2012). "The same authors showed that patients with Crohns disease, who have a mutation in NOD2 have a low level of expression of the defensins HD-5 and HD-6." (PMID 22862922, 2012). "Some studies have shown that human Crohn's disease associated “loss-of-function” mutations in Nod2 show reduced transcription of IL-10 in response to bacteria." (PMID 21387014, 2011). "NOD2 IVS8+158 gene mutation was initially reported to confer higher risk for Crohn's disease in Ashkenazi Jews." (PMID 21914217, 2011). "Estimates of the risk of developing Crohn's disease (CD) can be made using DNA testing for mutations in the NOD2 (CARD15) gene, family history, and smoking status." (PMID 21247480, 2011). "Several studies have tried to explain how Nod2 “loss of function” mutations contribute to the development of human Crohn's disease, a chronic inflammatory disorder." (PMID 21387014, 2011). "Mutations in human Nod2 have also been linked to the development of Crohn's disease, a chronic inflammatory bowel disease." (PMID 21387014, 2011). "With the expanding role of Nod2, it will be important to validate these results and determine if Crohn’s disease mutations disrupt this pathway." (PMID 21994779, 2011).
Crohn disease (continued). "The NOD2 gene mutations (chromosome 16q12-21) have been principally linked to both Crohn's disease and BS." (PMID 21914217, 2011). "A good example in this context is the association of CARD15 and NOD2 variations with the Blau syndrome and Crohn's disease." (PMID 21660243, 2011). "Loss of function mutations of the NOD-2 gene have been identified in approximately 15% of people affected with Crohn's disease and NOD-2 deficient mice have impaired resistance to mycobacterial infections." (PMID 22196128, 2011). "Analysis for gene-gene interactions between CEACAM6 and NOD2 variants regarding susceptibility to Crohn's disease (CD)." (PMID 21559399, 2011). "Several groups have independently demonstrated that Nod2 can function in the autophagy pathway in addition to signaling cascades, thus bridging two major Crohn’s disease susceptibility genes." (PMID 21994779, 2011). "These latest two studies represent the connection between the two genetic pathways that induce susceptibility to Crohn's disease: NOD2 and autophagy." (PMID 21490934, 2011). "The Crohn's disease synthetic association at NOD2 is again illustrative, as it is restricted to populations of European or Jewish descent." (PMID 21267062, 2011). "Mutations in NOD2 gene confer susceptibility to several chronic inflammatory disorders, including Crohn's disease and Blau syndrome." (PMID 21625457, 2011). "Mutations in NOD2 have been associated with chronic inflammatory disorders such as Crohn's disease and Blau syndrome." (PMID 21625457, 2011). "The role of allelic heterogeneity in complex disease is exemplified by the several, individually rare mutations in NOD2 associated with Crohn's disease." (PMID 21281506, 2011). "For instance, mice deficient in the Crohn’s disease gene Nod2 develop intestinal pathologies after infection with Helicobacter hepaticus or Citrobacter rodentium." (PMID 21994779, 2011). "Genetic and environmental factors influence susceptibility to Crohn's disease (CD): NOD2 is the strongest individual genetic determinant and smoking the best-characterised environmental factor." (PMID 21931826, 2011). "As NOD2 mutations have been generally associated with Crohn's disease, researchers also investigated the effects of NOD2 mutations on the expression of β-defensins." (PMID 21151692, 2010). "The functional importance of alternative splicing in 5'UTRs is exemplified by human NOD2, which is associated with Crohn's disease." (PMID 20222956, 2010). "Nod2 SNPs associated with Mycobacterial infections are in general distinct from those observed in Crohn's disease or the Crohn's disease SNPs confer protection against Mycobacterial-dependent diseases." (PMID 20531959, 2010). "Common NOD2 variants have been associated with Crohn's Disease (CD) and graft-versus-host disease (GVHD)." (PMID 21188221, 2010). "While polymorphisms in the Nod2 LRR domains confer sensitivity to developing Crohn's disease, mutations in the Nod2 NACHT domain are associated with other inflammatory disorders, such as Early-Onset Sarcoidosis and Blau syndromes." (PMID 20531959, 2010). "The compromised anti-bacterial activity demonstrated by the Crohn's-associated LRR domains should be considered alongside the signalling properties of the protein in any model of the molecular mechanisms associated with Nod2's role in Crohn's disease." (PMID 20531959, 2010). "Three distinct Nod2 single nucleotide polymorphisms (SNPs) have been associated with increased risk of developing Crohn's disease." (PMID 20531959, 2010). "Mutations in the leucine-rich repeat (LRR) domain of Nod2, a bacterial recognition protein, are associated with development of the inflammatory bowel disorder, Crohn's disease." (PMID 20531959, 2010). "NOD2 received great attention after it was identified as a susceptibility gene for Crohn's disease in 2001." (PMID 21151692, 2010).